IGF1 (insulin like growth factor 1)
Diseases named in the same sentence as IGF1 in open-access papers (continued):
Sharing a sentence is not in itself a finding about the gene and the disease.
cancer (continued). "Insulin-like growth factor (IGF1) was well known in cancer growth, and it was even suggested as a modified gene to cure cancers." (PMID 35280511, 2022). "Our finding generates an important tool to answer the question of how the GH/IGF1 axis drives the growth of cancer cells." (PMID 35966052, 2022). "Studies revealed that insulin has a more substantial effect on the survival of cancer cells, while IGF-1 was better in the cell cycle and proliferation." (PMID 35252207, 2022). "Cancer genes (e.g., tumor suppressors, oncogenes) adopt the IGF1 signaling pathway.Cellular and viral oncogenes require an intact IGF1 axis in order to elicit their transforming roles." (PMID 36479090, 2022). "Recent clinical data show how multiple dietary changes involving calorie intake reduction or FMDs are able to counteract growth-promoting factors—such as glucose, IGF-1, or insulin—in cancer." (PMID 35681689, 2022). "The insulin/IGF-1 pathway also plays a role in cancer progression, and its inhibition by Klotho is tumor suppressive." (PMID 35903083, 2022). "That binding activates signaling cascades which promote cancer aggression and inflammation, at least in part due to insulin-like growth factor 1 (IGF1) release." (PMID 36540765, 2022). "Biological activity IGF-1 is involved in cancer progression by preventing cell apoptosis and facilitating cell proliferation after binding to the IGF-1 receptor." (PMID 36048786, 2022). "Increased levels of free IGF-1 because of hyperinsulinemia have mitogenic and antiapoptotic properties, which can enhance cancer promotion and progression." (PMID 36079756, 2022). "As for GH1, PRKCG, and PSPN, they are not known prognostic biomarkers, but GH1 is still regarded as strongly related to cancer development because of its key role in the stimulation of growth factor secretion (i.e., IGF-1)." (PMID 36428747, 2022). "Additional to ETC inhibitory effects, metformin has been shown to reduce plasma levels of insulin and insulin-like growth factor 1 (IGF-1) to limit glucose availability in the glycolysis-dependent cancer cells." (PMID 35911555, 2022). "In an in vivo study, the presence of high IGF-1 levels in the primary tumor environment tended to induce cancer cells to metastasize to bone, and cancer cell lines that highly expressed IGF1R were prone to display enlarged bone mass." (PMID 35370981, 2022). "Insulin is itself a mitogen and increases the bioactivity of insulin-like growth factors (IGF-1), which can promote cancer by inhibiting apoptosis and stimulating cell proliferation." (PMID 36429506, 2022). "The genes observed in this network (CEACAM1, IGF1, MET, MMP1, MMP3 and WNT5A) were upregulated in cSII/III and are known to be linked to invasive properties in several other cancer types." (PMID 35022523, 2022). "IGF-1 has been proved to increase the proliferation rate of many cancers and lead to treatment resistance." (PMID 36235844, 2022). "Pancreatic fibroblasts have been reported to increase cancer dissemination and motility mediated by IGF1/IGF1R signaling under hypoxia, which is also reported to increase PI3K/Akt activity in fibroblasts as was observed in these data." (PMID 35565326, 2022). "Several theories of the biology determining the poor prognosis of cancer patients with high BMI were postulated including increased serum insulin-like growth factor-1 and involvement of fatty acid synthase (FASN) pathways." (PMID 34342680, 2022). "The involvement of IGF1 signaling in aging and cancer biology has been the focus of extensive research for several decades." (PMID 36291127, 2022). "Elevated circulating insulin/IGF1 levels and the upregulation of insulin/IGF receptor signaling have been implicated in the development of various cancers." (PMID 36142321, 2022). "Given its role in FASN mRNA and protein expression, we next explored the role of SRPK2 in de novo palmitate synthesis in cancer cells in response to IGF-1 exposure." (PMID 36096767, 2022).
cancer (continued). "The IGF‐1 pathway has been finely related to cancer and IBD, by regulating the immune system and through its multifunctional involvement in tumor microenvironment." (PMID 33510215, 2021). "The final mediator of the growth promoting action of GH is IGF-1, which exerts potent anti-apoptotic and mitogenic activity in all cells and is expressed and secreted from many different types of cancer cells." (PMID 32349463, 2021). "Consistent with the key role of IGF1 in cellular proliferation, epidemiological studies have shown that LS patients are protected from cancer development." (PMID 34769292, 2021). "Insulin‐like growth factor‐1 (IGF‐1) is a circulating polypeptide and the main potential mitogen for normal and neoplastic cells with a central role in cancer development and progression." (PMID 34528373, 2021). "The FMD-dependent reduction in blood glucose and IGF-1 levels is of interest given their key role in age-related diseases, including cancer." (PMID 34572814, 2021). "A recently published study reported that periodic fasting or a fasting-mimicking diet can enhance the anti-cancer activity of anti-estrogen therapies by lowering the circulating levels IGF-1, insulin and leptin and consequently inhibiting the AKT mTOR pathway." (PMID 33816477, 2021). "To date, the limited evidence on HGF, EGF, and IGF-1 and their effect on liver regeneration seems to support a beneficial effect on the regeneration process or in cancer recurrence." (PMID 34572344, 2021). "Inhibition of IGF-1 in some specific cancer types, such as pancreatic carcinomas, led to decreased cancer growth and metastasis." (PMID 34456716, 2021). "The growth hormone/insulin growth factor-1 (GH/IGF-1)/ insulin pathway and its downstream effectors, in fact, are known to promote aging and/or age-related diseases, including cancer, in many model organisms." (PMID 34572814, 2021). "The list of mediators, including TGF-β1, HGF, GRO-1, and IGF-1, depends on cancer and normal cell types." (PMID 33921783, 2021). "Of these, IGF-1R is overexpressed in cancer cells, has a crucial role in tissue development, and is activated by the hormone IGF-1." (PMID 34299089, 2021). "Experimental and epidemiological studies suggest that IGF-1 and its binding protein serum levels are influenced by dietary intake, and play a role in the pathogenesis of several common cancers." (PMID 34684639, 2021). "High IGF-1 gene expression signature mediating cancer proliferation and short survival in TNBC cells, and TQ targeting this site suggests a rationale for prevention and/or treatment." (PMID 35010954, 2021). "As a result of such studies, the IGF-1 signaling pathway became a target for new cancer therapeutics." (PMID 33557137, 2021). "IGF2 is highly expressed in a variety of tumor tissues, and activates the IGF1 signal pathway and promotes cancer progression on binding with IGF1R." (PMID 34335947, 2021). "For example, the insulin-like growth factor 1 (IGF-1) system performs multiple functions in the pathogenesis of different types of cancer." (PMID 35008759, 2021). "IGF-1R is the receptor for both IGF-1 and IGF-2, and several oncogenes targeting IGF-1R transcription have been reported to cause the overexpression of IGF-1R in cancers." (PMID 33669204, 2021). "Previous studies confirmed the vital role of IGF1 in the development of cancer by regulating cell proliferation and apoptosis." (PMID 34253194, 2021). "Aberrant IGF‐1 signaling has been observed in several cancers in humans, with the involvement of IGF‐1 receptor signaling in cancer cell proliferation, migration, and invasion as well as in resistance to therapeutic agents." (PMID 33510215, 2021). "Cathepsin G, a neutrophil-derived serine protease, induces cell migration, activates insulin-like growth factor 1, increases E-cadherin-mediated intercellular adhesion and cancer cell aggregation, and promotes cancer cell entry into blood vessels." (PMID 34674757, 2021).
cancer (continued). "For all these two cancer types, multivariable MR analysis adjusted for IGF1 showed consistent results." (PMID 34567085, 2021). "It is likely that TRAF4 and Nedd4 differentially regulate IRS-1 and IRS-2 ubiquitination and subsequent IGF-1 signaling in cancer cells." (PMID 33991522, 2021). "With the exception of a more uniformly positive relationship between IGF‐1 and cancer, these effects were remarkably consistent across a wide range of conditions, providing evidence for a unifying pathway that determines risk for most age‐associated diseases." (PMID 34363732, 2021). "Since cancer cells depend heavily on glycolysis, by reducing glucose, insulin, IGF-1 levels, plus lactate production, KDs potentially induce selective starvation in cancer cells." (PMID 34579079, 2021). "To conclude, our comprehensive pan-cancer analysis has characterized IGF-1/IGF-1R expression in different cancer cell lines and tissues." (PMID 34804946, 2021). "The linkage between life-long diminished IGF1 dosages and cancer evasion emphasizes the central role of this growth factor in the etiology of cancer." (PMID 34204736, 2021). "Collectively, these data support epidemiological and experimental evidence of a role for GH and IGF-1 in the development of cancer." (PMID 33816477, 2021). "Autocrine IGF-1 signaling is responsible for regulating cancer stem cell (CSC) related markers (e.g., CD44+, ALDH+, and EpCAM+) in MHCC97H cells." (PMID 33669204, 2021). "Pharmacological inhibition and genetic modification of K+-Cl− cotransport demonstrated that KCC is necessary for IGF-1-induced cancer cell invasiveness and proliferation." (PMID 35008759, 2021). "Most cancer cells highly express insulin and IGF-1, because they are important members of the tyrosine kinase class of membrane receptors and are highly homologous to tyrosine kinase oncogenes." (PMID 34485159, 2021). "Upon deletion of DICER, several molecules and receptor tyrosine kinases, which are involved in IR and cancer development, were hyperphosphorylated (IGF1, IR, IRS-2, and STAT3)." (PMID 34199293, 2021). "Accumulating evidence in the past few decades has revealed that IGF1 is abnormally expressed in various cancer types." (PMID 34253194, 2021). "These were novel findings that show how insulin and IGF1 downstream signaling cascades differ in cancer cells; however, the mechanisms for these differences were obfuscated by the distance of E-cadherin and ACC from the InsR and IGF1R signaling pathways." (PMID 34191793, 2021). "IGF‐1 is a 70‐amino acid polypeptide hormone and a major determinant in cancer development and pathogenesis." (PMID 34528373, 2021). "This phenomenon indicates that IGF‐1 from OSF has a potential role in increasing cancer progression in the OSCC microenvironment." (PMID 34528373, 2021). "Cancer-derived Hh also promoted the expression of growth factors such as IGF1 and GAS6 by fibroblasts, which reflected back on cancer cells." (PMID 34356110, 2021). "More importantly, the IGF-1/IGF-1R system mediates stimulatory effects in cancer cells via different routes such as the phosphatidylinositol-3kinasw(PI3K)/Akt1, mTOR, and MAPK." (PMID 35010954, 2021). "Increased levels of insulin-like growth factor-1 (IGF-1) and its receptor generally occur in OS and in other cancers, and also activate the PI3K/Akt-mTOR pathway, promoting tumor growth." (PMID 34715874, 2021). "KCC4-specific siRNA significantly attenuated endogenous cellular invasiveness of cancer cells, and the residual cellular invasiveness was much less sensitive to IGF-1 or EGF stimulation." (PMID 35008759, 2021). "In terms of mechanism, DNA damage repair is the most critical reason for the radiotherapy resistance of GH and IGF1 in cancer cells and damage repair effect on adjacent tissues." (PMID 34178997, 2021). "High levels of circulating IGF-1 and low levels of IGFBP-3 are associated with an increased risk of several cancers, including those of the prostate, breast, colon and lung." (PMID 34452353, 2021).
cancer (continued). "Aberrant signaling through insulin (Ins) and insulin-like growth factor I (IGF1) receptors contribute to the risk and advancement of many cancer types by activating cell survival cascades." (PMID 34191793, 2021). "GH and IGF1, as critical endocrine factors are involved in promoting cell proliferation and inhibiting cell apoptosis in cancer cells and normal cells." (PMID 34178997, 2021). "Yet, hyperinsulinemia can be detrimental in cancer, because insulin and IGF-1 promote cancer cell growth." (PMID 33801684, 2021). "IGF-1 modulates cell growth, metabolism, and survival, and is thought to be important in cancer initiation and progression." (PMID 34583967, 2021). "Correlation occurred more frequently between the presence of this IGF-1R polymorphism, serum IGF-1 concentration and more advanced CRC than cancer in the early stages." (PMID 34208601, 2021). "For example, the IGF1/PI3K/Akt/mTOR system is often hyperactive in cancer cells due to chronic hyperglycemia and hyperinsulinemia, as well as the mutations in genes that code for pathway proteins." (PMID 34579079, 2021). "The PI3K p110α inhibitor BYL719 (alpelisib) is currently an approved cancer therapeutic; however, genetic studies in rodents suggest that long-term suppression of insulin/IGF1 signaling mediated PI3K p110α can extend life and healthspan of aged mice." (PMID 33503847, 2021). "In the MCF-7 cancer cells, the migration rate upon 100 ng/mL vimentin and 100 ng/mL IGF-1 treatments, these reached 2.5 and 3 times higher than control respectively." (PMID 34299089, 2021). "Expression of the respective receptors is detected on cancer cells of different origins and several cancers are driven by insulin and IGF-1 in vitro." (PMID 33987528, 2021). "The growth hormone (GH)–insulin-like growth factor-1 (IGF1) endocrine axis is a central player in normal growth and metabolism as well as in a number of pathologies, including cancer." (PMID 34769292, 2021). "In summary, in mice there is very strong evidence for the link between high growth hormone and IGF-1 levels, DNA damage and cancer, likely mediated at least in part by the activation of AKT, TOR-S6K and PKA signaling, analogously to what is observed in yeast." (PMID 34572814, 2021). "In cancer, GH, via its mediator peptide insulin-like growth factor-1 (IGF-1) is known to influence regulation of cellular growth." (PMID 33762603, 2021). "Previously, ERK1/2 and AKT signaling cascades have emerged as pivotal transduction mediators involved in IGF1-dependent responses in cancer cells." (PMID 33557316, 2021). "Numerous studies have demonstrated that IGF1 signaling is involved in tumor growth and is a prognostic factor for different cancer types." (PMID 34178997, 2021). "The overexpression of IGF-1 and its receptor IGF-1R have been implicated in carcinogenesis and are also considered risk factors for the progression of diverse human cancers." (PMID 34804946, 2021). "Intermittent fasting impacts multiple cancer related pathways, including reducing IGF-1 and increasing IGF1BP by negatively regulating growth hormone-mediated IGF-1 mRNA production." (PMID 33815289, 2021). "IGF-1 increases VEGF expression in cancer cells through binding to its receptor promotes angiogenesis." (PMID 33836774, 2021). "It is suggested that if studies correlated with high IGF-1, GH levels, and high cancer incidence are conducted through high-sensitive measures of today’s technology, lower standardized incidence rate is detected." (PMID 34530525, 2021). "We obtained 604 GVs strongly and independently predicting IGF1, which also all were available for cancer and neoplasm." (PMID 34567085, 2021). "Conversely, glucose restriction can inhibit various energy‐dependent pathways such as IGF‐1/PI3K/Akt/mTOR in cancer cells, suppress cell metabolism and growth, and promote G1 phase arrest and apoptosis." (PMID 32678516, 2020).
cancer (continued). "Growth factor sequestration by IGFBP-3-Fc enhances the activity of EGFR inhibitors by decreasing cell survival and inhibiting bFGF, HGF, and IGF1 growth factor rescue and also potentiates the activity of other cancer drugs." (PMID 32066763, 2020). "Homeostasis regulation of insulin and IGF-1 levels activate various pathways to mediate cell proliferation and survival, which can promote cancer cell proliferation and invasion or inhibit apoptosis." (PMID 32370764, 2020). "IGF-1 has been shown to be essential for mitochondrial biogenesis and turnover in cancer cells and plays a protective role in regulating mitochondrial function." (PMID 31732912, 2020). "The enrichment of the identified proteins seem to implicate “14-3-3 mediated signaling,” “cell cycle: G2/M DNA damage checkpoint regulation,” and “ERK5, VEGF, IGF1, and p70S6K signaling,” all of which are important in cell plasticity and cancer progression." (PMID 33117671, 2020). "Further understanding of IGF1/IGF1R signaling is required to elucidate the significance of IGF1R expression levels in cancer development and malignancy." (PMID 32033461, 2020). "Among the genes with increased 5hmC density in PDAC were those related to pancreas development (GATA429, GATA629, PROX130, ONECUT131, and MEIS232) and/or implicated in cancer (YAP133, TEAD133, PROX134, ONECUT2, ONECUT1, and IGF1)." (PMID 33077732, 2020). "A similar situation occurs with the IGF-IR (insulin-like growth factor-1), a family member of insulin receptors that is enhanced in different cancer types." (PMID 33643916, 2020). "Both PDGF and IGF-1 signaling pathways contributed to tumor growth, angiogenesis, and metastatic activities in various cancers as binding to the receptors." (PMID 32640634, 2020). "IGF-1-mediated induction of BNIP3 expression was observed in all cancer cell lines tested, including MCF-7 cells." (PMID 31936236, 2020). "Excess insulin directly or indirectly regulated the activity of insulin-like growth factor-1 (IGF-1), which was an important cytokine that influenced the development and progression of cancer." (PMID 32709224, 2020). "Here, we delineated the signaling pathway for IGF-1-mediated BNIP3 induction in cancer cell lines and mouse embryonic fibroblasts MEFs." (PMID 31936236, 2020). "High levels of IGF-1 and IGF-2 are linked to the growth of cancer or with cancer recurrence in cancer survivors." (PMID 32399389, 2020). "In physiological conditions, its antiapoptotic effect can help cell survival; while in pathophysiological conditions, IGF1 can lead to cancer or increment of adipocytes." (PMID 32974138, 2020). "Declines of plasma levels of insulin like growth factor-1 (IGF-1), insulin and glucose are among the mediators of the effects of fasting on cancer cells, as these factors can promote growth and prevent apoptosis." (PMID 32576828, 2020). "Platelets can secrete tumor growth factors, such as VEGF, TGF-β, platelet-derived growth factor (PDGF), and insulin-like growth factor-1 (IGF1), which play critical roles in cancer angiogenesis and metastasis." (PMID 32624701, 2020). "Alterations in insulin and insulin-like growth factor type 1 (IGF-1) signalling pathways have been identified as the main drivers that lead to the development of both diabetes and cancer." (PMID 32708201, 2020). "The relationship between the IGF-1 pathway and tumor development had been shown in various cancer types such as lung, prostate, breast, gynecological, and gastrointestinal cancers." (PMID 32907593, 2020). "Counterintuitively, high levels of IGF1 in the plasma and cytoplasm of the cancer cells seem to be a prognostic for the improved survival in cancer patients." (PMID 33260481, 2020). "Overall, the studies on IGF-II physiological binders are in agreement with the genetic studies supporting a distinctive cancer-promoting role for this IGF, differentiating it from its related cousin, IGF-1." (PMID 32033443, 2020).